LINC00853 (long independently transcribed non-coding RNA 853)
Synonyms: ncRNA-a4; PDZK1IP1-AS1
Gene: Long non-coding RNA gene on chromosome 1 (47,179,250 to 47,180,613, forward strand). Ensembl gene ENSG00000224805.
Diseases named in the same sentence as LINC00853 in open-access papers:
LINC00853 is named in the same sentence as 8 diseases in open-access papers, as found by Europe PMC text mining. Sharing a sentence is not in itself a finding about the gene and the disease. The quoted sentences say what the papers report.
hepatocellular carcinoma (4 papers, 2020 to 2024). A malignant tumor that arises from hepatocytes. "In the early stages of hepatocellular carcinoma, serum small extracellular vesicle derived LINC00853 may provide a new diagnostic biomarker." (PMID 37403034, 2023). "All lncRNAs selected in this study have established roles in HCC pathogenesis, UCA1, GAS5, LINC00152, and LINC00853, were chosen based on their established functional relevance in hepatocellular carcinoma (HCC) and their demonstrated potential as diagnostic biomarkers." (PMID 39609501, 2024).
gastric cancer (2 papers, 2023 to 2024). A primary or metastatic malignant neoplasm involving the stomach. "Therefore, MAP17 and LINC00853 co-operatively promote carcinogenic activity and signaling pathways associated with gastric cancer." (PMID 38586313, 2024). "The expression of LINC00853 was significantly elevated in four gastric cancer cell lines (AGS, MKN45, MKN 74, and KATOIII) compared to a normal cell line (GES-1)." (PMID 38586313, 2024). "LINC00853 was secreted as a component of EXO in gastric cancer, and exosomal LINC00853 exerted oncogenic effects through MAP17-related cell signaling pathways in gastric cancer cells." (PMID 38586313, 2024). "To confirm the aberrant expression of exosomal LINC00853 in gastric cancer, we collected plasma samples from three patients and culture medium from AGS gastric cancer cells and examined the EXO and EXO-depleted supernatant (EDS)." (PMID 38586313, 2024). "LINC00853 facilitated the proliferation, epithelial–mesenchymal transition, invasion, and migration of gastric cancer cells." (PMID 38586313, 2024). "We further verified the expression of LINC00853 in 100 patients who had undergone surgical resection for gastric cancer." (PMID 38586313, 2024). "In conclusion, our study confirmed that exosomal LINC00853 is a potential biomarker of gastric cancer and revealed its regulatory effects on the MAP17/PDZK1/AKT pathway in gastric cancer." (PMID 38586313, 2024). "Therefore, siRNA-mediated knockdown of LINC00853 resulted in decreased LINC00853 expression in EXO, which aggravated the oncogenic effect of exosomal LINC00853 in gastric cancer cells." (PMID 38586313, 2024). "To elucidate the mechanism of regulation of the biological functions of gastric cancer by LINC00853, we analyzed candidate genes that could be regulated by the cis-regulatory mechanism of LINC00853." (PMID 38586313, 2024). "Therefore, LINC00853 promoted the invasion, migration, and colony formation of gastric cancer cells." (PMID 38586313, 2024). "We also examined whether LINC00853 in the EXO affected the proliferation of gastric cancer cells." (PMID 38586313, 2024). "Thus, LINC00853 and MAP17 may act as co-operative oncogenes in gastric cancer." (PMID 38586313, 2024). "The expression levels of LINC00853, LINC00634, LINC01535, GAPLINC, and AC017002.1 were significantly higher in gastric cancer tissues than in non-cancerous adjacent tissues (P ≤ 0.05), confirming that these five lncRNAs were differentially expressed in the EGC samples." (PMID 38586313, 2024). "Among them, LINC00853 was the most important lncRNA that showed significantly increased expression in EGC and advanced gastric cancer samples compared to non-tumor tissues in endoscopic biopsy samples collected from our institute and the GTEx and TCGA datasets." (PMID 38586313, 2024).
gastric tumor (1 paper, 2024). "We investigated the functional correlation between gastric tumor formation and exosomal LINC00853." (PMID 38586313, 2024).
lymph node metastasis (1 paper, 2023). "Besides, the over-expression of LINC00853 was strongly associated with lymph node metastasis." (PMID 37403034, 2023).
T-cell acute lymphoblastic leukemia (1 paper, 2023). Acute lymphoblastic leukemia of T-cell origin. "LINC00853 has been reported to regulate the level of CC chemokine receptor 9 (CCR9) modulating the binding of CCR9 and CC chemokine ligand 25 (CCL25), which was involved in the process of the infiltration of T cell acute lymphoblastic leukemia." (PMID 37403034, 2023).
cancer (4 papers, 2020 to 2024). A tumor composed of atypical neoplastic, often pleomorphic cells that invade other tissues. "Our analysis highlighted LINC00853, which was significantly upregulated in cancer tissues and implicated in promoting epithelial-mesenchymal transition via the MAP17/PDZK1/AKT pathway." (PMID 38586313, 2024). "MAP17 is a neighboring gene of LINC00853 and is a representative oncogene mainly expressed in various cancers." (PMID 38586313, 2024). "Further study indicated that LINC00853 promoted cell proliferation, migration and cancer stemness while suppressed cell apoptosis." (PMID 37403034, 2023). "Considering that little is known about LINC00853 and its roles in cancer, this is an area that warrants further research." (PMID 32525601, 2020). "LINC00853 exerted a cancer-promoting role in GC through FOXP3-mediated transcription of PDZK1IP1." (PMID 37403034, 2023). "The expression of LINC00853 was significantly higher in cancer tissues than in non-tumor tissues (P ≤ 0.001)." (PMID 38586313, 2024).
tumor (4 papers, 2020 to 2024). "Results for tumor morphology, growth curves, and weight revealed that down-regulation of LINC0085 effectively inhibited tumor growth in mice, while up-regulation of LINC00853 remarkably promoted tumor progression." (PMID 37403034, 2023). "Taken together, these findings revealed the tumor-promoting activity of LINC00853 in GC, expanding our understanding of lncRNAs regulation on GC pathogenesis." (PMID 37403034, 2023). "In vivo and in vitro functional experiments, we revealed that LINC00853 promotes GC proliferation, migration, and tumor stemness." (PMID 37403034, 2023). "Subsequently, LINC00853 knockdown cells were subjected to tumor xenograft tests and exhibited decreased tumor growth in nude mice." (PMID 37175629, 2023). "Considering that tissue expression of LINC00853 increased with tumor progression in TCGA_LIHC dataset, prognostic performance of EV‐LINC00853 ought to be evaluated in a larger number of patients to confirm these results." (PMID 32525601, 2020). "Furthermore, the serum-free sphere formation assay revealed that LINC00853 knockdown reduced tumor spheres growth while overexpression of LINC00853 facilitated spheres growth." (PMID 37403034, 2023). "Here we hypothesized that LINC00853 modulated tumor progression and stemness through regulation of PDZK1IP1." (PMID 37403034, 2023). "Next, we evaluated the regulation of LINC00853 in tumor growth in vivo." (PMID 37403034, 2023). "Besides, immunohistochemical analysis for Ki67 indicated that knockdown of LINC00853 dramatically facilitated Ki67 levels, while overexpression of LINC00853 notably inhibited Ki67 expression in tumor tissues." (PMID 37403034, 2023). "Finally, we subjected cells with knocked-down LINC00853 to tumor xenograft tests." (PMID 37175629, 2023). "Mechanistically, LINC00853 promoted PDZK1IP1 expression through binding to FOXP3, thus maintaining tumor stemness and accelerating tumor progression." (PMID 37403034, 2023). "According to the information of Ensembl database, LINC00853 is located upstream of gene PDZK1IP1 (MAP17), and PDZK1IP1 is also found to be highly expressed in tumors and related to tumor cell stemness." (PMID 37403034, 2023).
LINC00853 also shares sentences with these, for which no sentence is quoted: liver disease (1 paper).